MSLN (mesothelin)
Diseases named in the same sentence as MSLN in open-access papers (continued):
Sharing a sentence is not in itself a finding about the gene and the disease.
lung carcinoma (74 papers, 2011 to 2025). "Our analysis suggests that ADCs targeting MSLN may be particularly beneficial in lung cancer patients harboring dual mutations in STK11 and KEAP1 genes." (PMID 39186767, 2024). "Using flow cytometry with specific antibodies, we verified the presence of MSLN on the A549 lung cancer cell line with a notably high antigen expression density." (PMID 40181405, 2025). "CAR-T cells targeting EGFR, CEA, and MSLN have been carried out for patients with lung cancer in clinical trials." (PMID 40624569, 2025). "MSLN is a glycosylphosphatidylinositol-anchored protein found on the cell surface, which many tumors express at high levels, particularly lung cancer." (PMID 40922740, 2025). "To assess the anti-tumor functionality of CAR-T cells expressing this CCR, we constructed two distinct CAR-T cell models: MSLN CAR targeting lung cancer cells and CD19 CAR targeting hematological malignancies." (PMID 40181405, 2025). "Due to dual expression of mesothelin (MSLN) in both lung cancer and normal mesothelium, the development of mesothelin-specific CAR-T cell therapy that incorporates an HLA-gated safety mechanism can selectively kill MSLN(+)A*02(-) malignant cells." (PMID 38659003, 2024). "Prior investigations have unveiled a positive correlation between MSLN overexpression in lung cancer patients and unfavorable prognoses." (PMID 38622705, 2024). "In this study, we found that MSLN is not only a specific expression of the tumor antigen in situ in lung cancer compared to paracancer, but its expression is further elevated in brain metastases." (PMID 38570866, 2024). "The antitumor element of the TriKE used here targeted mesothelin (SS1 TriKE) that can be found on the lung cancer cell line H460." (PMID 39475618, 2024). "If NK cell responses can be boosted in addition to enhanced targeting of mesothelin+ lung cancer cells, this dual improvement in immune responses has the potential to succeed where other strategies targeting mesothelin have failed." (PMID 36911670, 2023). "Blood MPF and MSLN levels were correlated, with modest accuracy, for malignant pleural mesothelioma and lung cancer." (PMID 36968141, 2023). "While mesothelin targeting still holds promise in the treatment of lung cancer, new approaches are necessary to enhance efficacy whilst limiting toxicity." (PMID 36911670, 2023). "Mesothelin (MSLN) is a cell surface glycoprotein and a tumor differentiation marker expressed in multiple tumors, including lung cancer and MPM." (PMID 35884975, 2022). "Supplementing mesothelin- or MPF-stimulated growth in MSLN knockout mice promoted lung cancer growth, demonstrating that mesothelin in the microenvironment promotes cancer growth and metastasis in vivo." (PMID 35326701, 2022). "Lung cancer cells with mesothelin knockdown had reduced anchorage-independent growth, tumor formation, migration, invasion, and metastasis, indicating that mesothelin is a mediator of these important cancer hallmarks." (PMID 35326701, 2022). "MSLN, a cell surfaced glycoprotein, is overexpressed in the majority of cancer types including lung cancer, mesothelioma, pancreatic cancer, and ovarian cancer." (PMID 35720364, 2022). "MSLN was immunohistochemically evaluated in 596 lung carcinomas of different types by Miettinen M and Sarlomo-Rikala M in 2003." (PMID 31463062, 2019). "Our team previously demonstrated that MSLN was also a promising target for treating lung cancer and gastric cancer." (PMID 31463062, 2019). "In lung cancer, accumulating evidence indicates that high expression of MSLN is correlated with poor patient’s overall prognosis and relapse-free survival." (PMID 28288645, 2017). "In the advanced lung cancer setting, prior studies of mesothelin expression are retrospective, involved small number of patients and a very heterogeneous population." (PMID 26028668, 2015). "In this study, we used prospectively obtained clinical and pathological data to characterize mesothelin expression in lung cancer." (PMID 26028668, 2015).
lung carcinoma (continued). "We used the lung cancer cell line A549, which has very low expression of MSLN (average of 3.5×103 mMSLN binding sites/cell) but robust expression of CA125." (PMID 25118887, 2014). "Intelectin-1 was expressed in only 1 of 88 cases of lung cancer, whereas calretinin, CK 5/6, podoplanin, and mesothelin were expressed in about 23%, 44%, 14%, and 40% of lung cancers, respectively." (PMID 22768319, 2012). "MSLN’s involvement as cancer hallmarks is highlighted by the reduction in carcinoma development, migration, invasion, metastasis and anchorage-independent growth shown in lung cancer cells following MSLN knockdown." (PMID 40227616, 2025). "The introduction of the cytoplasmic domain of DAP10 into second-generation CARs M28z and G28z to create M28z10 and G28z10, targeting mesothelin (MSLN) and glypican 3 (GPC3) respectively, resulted in enhanced and prolonged effector function against MSLN+ lung cancer cell lines." (PMID 40612946, 2025). "In lung cancer, MSLN promotes epithelial-mesenchymal transition (EMT) and stemness of tumor cells, tumorwhich may facilitate the occurrence of BM." (PMID 38570866, 2024). "Additionally, MSLN has been shown to facilitate epithelial-mesenchymal transition (EMT) in lung cancer and malignant mesothelioma." (PMID 38628720, 2024). "MSLN is considered to be a promising target because it is overexpressed in 69 % of lung adenocarcinomas and promotes the development and metastasis of lung cancer cells." (PMID 38475858, 2024). "Together these findings indicate that MSLN is involved in malignant progression of lung cancer and may play an important role in promoting BM in NSCLC." (PMID 38570866, 2024). "MSLN is highly expressed in multiple malignant cancers, including lung cancer." (PMID 37308954, 2023). "CAR-T cells targeting EGFR variant III, mesothelin, Erythropoietin-producing hepatocellular carcinoma A2 (EphA2), Delta-like 3 (DLL3), PSCA- and MUC-1, and PD-L1 have shown significant antitumor effects against lung cancer cells in vitro and in vivo." (PMID 37420216, 2023). "Mesothelin is possibly the second most targeted antigen in lung cancer CAR-T clinical trials." (PMID 35455052, 2022). "MSLN, a tumor differentiation antigen with the low expression on normal mesothelial cells, is overexpressed in a wide range of solid cancers, including lung cancer, mesothelioma, and pancreatic carcinoma; therefore, it could be used as a potential target." (PMID 34790207, 2021). "Similarly, MSLN was also reported in 25 to 67% of triple negative breast cancer and in 60 to 70% of lung cancers." (PMID 32517181, 2020). "However, mesothelin is present in a wide range of tumors including ovarian and lung cancers (60–65%), and also PDAC-derived tumors (80–85%)." (PMID 31658755, 2019). "Inhibition of MSLN reversed mesenchymal features and attenuated stem cell properties, in addition to inhibiting tumor growth and metastasis in lung cancer models; this could be exploited also for thyroid cancer." (PMID 31430969, 2019). "This has implications for the MESOMARK kit for detection of soluble mesothelin as other tumor types including some lung cancers with similar presentations may produce soluble mesothelin." (PMID 21984916, 2011). "Specifically, we questioned whether treatment induced a humoral response to mesothelin, a protein that has been shown to be overexpressed in pancreatic, gastric, ovarian, and lung carcinoma." (PMID 24212806, 2011). "In fact, other studies using breast and lung cancer cell lines have demonstrated that MSLN expression confers an advantage to cell survival and proliferation in suspension, which is a feature that may be important for the peritoneal dissemination of floating cancer cells in the peritoneal cavity." (PMID 32612258, 2020). "In a study focused on lung cancer treatment, researchers developed dual-target CAR-T cells simultaneously targeting MSLN and PD-L1." (PMID 40904456, 2025).
lung carcinoma (continued). "A series of antigens targeting surface proteins, including EGFR, CEA, MSLN, HER2, ROR1, MUC1, and DLL3 in lung carcinoma cells have been incorporated into CAR structure to allow CAR-T cells target lung cancer tissue." (PMID 40624569, 2025). "EGFR, MSLN, MUC1, CEA, PD-L1, ROR1, HHLA2 (also referred to as B7H7), HER2, and various other target antigens are being studied for CAR-T therapy in lung cancer." (PMID 38622705, 2024). "Mesothelin (MSLN) is a tumor differentiation antigen that has recently been found to be overexpressed in many types of solid tumors, including lung cancer." (PMID 38570866, 2024). "Some of the current targets for CAR T cells therapy in lung cancer are as follows: EGFR, HER2, mesothelin (MSLN), MUC1, CEA, PD-1, and CD80/CD86." (PMID 36899885, 2023). "Current antigen targets in clinical trials for CAR-T cell therapy for lung cancer include MUC-1, CEA, HER2, mesothelin, receptor tyrosine kinase-like orphan receptor 1 (ROR1), glypican-3 (GPC3), EGFR, and PD-1." (PMID 37420216, 2023). "In lung cancer, the most relevant therapeutic targets include ROR1, EGFR, PD-L1, CD80/CD86, mucin 1 (MUC1), mesothelin (MSLN), carcinoembryonic antigen (CEA), prostate stem cell antigen (PSCA) and human epidermal growth factor receptor 2 (HER2)." (PMID 36873868, 2023). "This prompted the development of MSLN-targeted CAR-T cells, and research using in vivo subcutaneous mouse lung cancer models and ex vivo models revealed a slower tumor growth rate and inhibitory effects on cell proliferation." (PMID 35720364, 2022). "In lung cancer, common targets such as MSLN, MUC1, PSCA, and epithelial cell adhesion molecule, have intratumoral heterogeneity, leading to an unsatisfactory outcome of CAT-T cell therapy in lung cancer." (PMID 34790207, 2021). "Experimental validation confirmed the unique over-expression of predicted surface markers (MUC4, MSLN, and SLC7A11) in lung cancer cells at the protein level." (PMID 29560830, 2018). "The presented mechanism of enhancement of the WT1TCR signaling by NFAT-regulated CAR can be modified to target different WT1-positive tumors, such as ovarian and lung carcinoma, by using inducible CAR specific to surface antigens such as mesothelin, Her2, or folate receptor alpha." (PMID 40735486, 2025). "For instance, in studies focused on lung cancer therapy, PTX was co-incubated with Liposome-CAR-T-Exosomes targeting MSLN/PD-L1 for 40 minutes, followed by dialysis purification, successfully generating a Liposome-CAR-T-Exosomes@PTX complex exhibiting therapeutic effects." (PMID 40904456, 2025). "Epitope spread responses were measured by IFNγ ELISpot after short in vitro stimulation with a mixture of HLA class II-binding epitopes derived from various TAAs expressed in lung cancer, such as NY-ESO-1, KK-LC-1, mesothelin, and mK-RAS, and with HLA class I peptides from hTERT." (PMID 40543509, 2025). "In case of lung cancer, various targets like HER2, EGFR, MAGE-A1, MUC1, mesothelin (MSLN), CEA, inactive Tyrosine-protein kinase transmembrane receptor ROR1, PD-L1, B7-H3 and Chemokine receptor CXC4 have been identified and clinical studies have already been performed." (PMID 40922740, 2025). "Moreover, several of the targets previously discussed with other solid tumors, such as HER2, EGFR, ROR1, MSLN, PD-L1, MUC1, and CEA, are also currently being studied for CAR-T cell treatment for lung cancer." (PMID 38892913, 2024). "A study showed that knockdown of MSLN significantly inhibits in vitro cell adhesion, migration, and invasion (critical steps necessary for metastasis), and also reverses EMT and attenuates stem cell properties in lung cancer cells." (PMID 38570866, 2024). "Finally, VEGFR2, MAGE-A1, MAGE-A4, PSCA, AXL, Claudin 18.2, TGFB, CD22, ROR1, OX40, DLL3, MSLN, and EpCAM are being targeted in CAR-T cell clinical trials for lung cancer." (PMID 35455052, 2022).
lung carcinoma (continued). "Research into the use of BiTEs which target mesothelin are currently underway in triple-negative breast cancer, pancreatic ductal adenocarcinoma, lung cancer, and other solid tumors." (PMID 35326701, 2022). "Subsequent studies however suggested that sensitivity and specificity of mesothelin in reference to various types of pleural diseases and lung cancer was not as great as reported in the initial study." (PMID 28335760, 2017). "To test our hypothesis, we firstly mixed CARPD-L1z T cells and anti-mesothelin CAR T cells (CARMSLNz T cells) with 1: 1 ratio and co-cultured them with H460-MSLNGL that expressed Mesothelin, an antigen widely expressed in lung cancer and gastric cancers." (PMID 32514352, 2020). "Our results suggest that mesothelin targeted therapies could be useful in patients with KRAS mutant lung cancer, a subtype for which no targeted therapies are currently available." (PMID 26028668, 2015).
breast carcinoma (59 papers, 2012 to 2026). "The association between MSLN expression and clinical outcomes of ovarian, lung, breast cancers and PDAC patients has been extensively studied." (PMID 32517181, 2020). "A third of breast cancers overexpress mesothelin, a 40-kDa membrane-associated glycoprotein playing a major role during tumor progression." (PMID 32235331, 2020). "Other studies have demonstrated that the expression of MSLN in the luminal membrane can be correlated with a worse prognosis than that associated with its cytoplasmic expression in gastric carcinoma, extrahepatic bile duct cancer, and breast cancer." (PMID 35565412, 2022). "MSLN, when overexpressed in breast cancer cells, causes sustained activation of ERK1/2." (PMID 23209424, 2012). "To explore the clinical relevance of MSLN in liver metastasis of BC, we evaluated MSLN expression in the breast cancer TCGA database online using the UALCAN website and observed that MSLN exhibited higher expression level in TNBC compared to other BC subtypes." (PMID 41513618, 2026). "To substantiate this finding, we overexpressed MSLN in wild-type human TNBC cells (BT549) and murine mammary carcinoma cells (E0771), both exhibiting intrinsically low MSLN expression." (PMID 41513618, 2026). "Mesothelin (MSLN) overexpression has been shown to occur in a number of solid tumors, including breast cancer, particularly in more aggressive and advanced subtypes of the disease." (PMID 39755633, 2025). "CAR T-cell therapy in breast cancer has shown early promise, particularly in HER2-positive breast cancer, with several clinical trials underway that target different antigens such as mesothelin, EGFR, and folate receptor-alpha." (PMID 40940995, 2025). "Analysis of the genomic alteration frequencies demonstrated the highest proportion of MSLN amplification in breast cancer and EOC (4%, and 2%, respectively)." (PMID 40402266, 2025). "Patients with breast cancer who overexpress MSLN are more likely to experience poorer clinical outcomes and develop chemotherapy resistance." (PMID 39755633, 2025). "CAR-Ms targeting VEGFR and MSLN have been investigated for breast cancer treatment, and suitable targets await further investigation." (PMID 38680498, 2024). "Breast cancer patients with MSLN overexpression are correlated with poor clinical outcomes and a greater risk of developing chemo-resistance." (PMID 35414783, 2022). "Its expression has been found to be upregulated in various types of cancers, including breast cancer, making MSLN-targeted CAR-T cells a potential opinion in breast cancer therapy." (PMID 35935930, 2022). "In in vitro and in vivo xenograft models of breast cancer, MSLN-targeted CAR-T cells specifically damaged MSLN-positive breast cancer cell lines and prominently inhibited the growth of breast cancer tumors." (PMID 35935930, 2022). "Mesothelin (MSLN) is a cell-surface tumor antigen expressed in different subtypes of breast and non-breast cancer." (PMID 33418877, 2021). "By further engineering the STING KO cell line with a chimeric non-secretable MSLN receptor for proper MSLN-THV manufacturing, our proof-of-concept study proposes MSLN-THV as potential candidates for preclinical evaluation of breast cancer models." (PMID 33418877, 2021). "MSLN was rare in cancers of the breast (7% of 1138), kidney (7% of 807), thyroid gland (1% of 638), soft tissues (0.3% of 931), and prostate (0 of 481)." (PMID 33917081, 2021). "In breast cancer cells cultured in suspension, overexpression of MSLN (via ectopic expression) was reported to favor ERK1/2 in an active state and to decrease Bim levels—Bim being an important inducer of anoïkis." (PMID 32517181, 2020). "Within the subset of breast cancer samples for which we were informed on the molecular subtype classification, we observed a high MSLN amplification rate within the basal-like subtype (33% of N = 378)." (PMID 26172299, 2015).